IRF3 (interferon regulatory factor 3)
Diseases named in the same sentence as IRF3 in open-access papers (continued):
Sharing a sentence is not in itself a finding about the gene and the disease.
cardiovascular diseases (3 papers, 2022 to 2025). "Our results showed that C-176 could inhibit HG-induced STING expression, as well as downstream IRF3/NF-κB signalling, which is consistent with previous studies on the effect of C-176 on renal and cardiovascular disease." (PMID 38129863, 2023). "The genetic deletion of key molecules in this pathway, such as CGAS, STING1, and interferon regulatory factor 3, affords salubrious effects, including improving survival and cardiac dysfunction, rendering the CGAS-STING1 pathway an attractive therapeutic target in cardiovascular disease." (PMID 40180542, 2025). "Finally, IRF3 also has been targeted in the setting of other cardiovascular diseases but not in the context of DNA damage, and therefore, such studies are not discussed." (PMID 40180542, 2025).
vasculopathy (3 papers, 2019 to 2022). "STING-associated vasculopathy also develops independently of IRF3 in mice." (PMID 33488589, 2020). "In this regard, a mouse model of STING-associated vasculopathy with onset in infancy that harbors gain-of-function mutations of STING developed inflammation even in the absence of IRF3." (PMID 34901991, 2022).
immune disorders (2 papers, 2013 to 2023). "The new way of regulating IRF3 phosphorylation will provide insight into the understanding of IFN-I production in the innate response and possible intervention of the related immune disorders." (PMID 37673879, 2023).
kidney diseases (2 papers, 2023). "Irf3 deletions create a dramatic renal disease phenotype in infected mice due to the loss of the IRF3-dependent defense, including IFN-β, and the overexpression of Irf7 and IRF7-dependent gene networks." (PMID 38251349, 2023). "Pitx1, IRF3, and ETS1 are also TFs involved in the pathogenesis of kidney diseases." (PMID 36967395, 2023).
neurodegenerative disease (2 papers, 2022 to 2025). A disorder of the central nervous system characterized by gradual and progressive loss of neural tissue and neurologic function. "In neurodegenerative diseases, IRF3 serves as a key transcription factor in TLR signaling pathways, responsible for activating the expression of type I interferons and other inflammation-related genes." (PMID 40243463, 2025). "Furthermore, IRF3 activation is a key step in the STING pathway, which exacerbates neuroinflammation in neurodegenerative diseases, including MS, via the production of downstream factors such as IFN-β." (PMID 40243463, 2025).
neurodevelopmental disorder (2 papers, 2024). A behavioral and cognitive disorder with onset during the developmental period that involves impaired or aberrant development of intellectual, motor, or social functions. "Interestingly, signaling pathways implying irf3 maternal activation during development have been associated with the onset of neurodevelopmental disorders (NDDs)." (PMID 38674426, 2024). "HACE1, along with UPS proteins, shows an anti-inflammatory effect by downregulating the IRF3 and NF-κB activation pathways, hence showing the involvement of UPS and HACE1 in immune-related pathogenesis and neurodevelopmental disorders." (PMID 38790209, 2024).
psychiatric disorder (1 paper, 2022). A disorder characterized by behavioral and/or psychological abnormalities, often accompanied by physical symptoms. "Considerable evidence suggests that type I IFN is associated with psychiatric disorders, and that the production of type I IFNs as a result of TLR4 induced IRF3 activation and TLR7 induced IRF7 activation may be closely associated with IFN-mediated psychiatric disorders." (PMID 36325336, 2022).
reproductive disease (1 paper, 2024). "Thus, the IRF3/7 DKO mouse-BUNV infection system, which produces this clinical phenotype, may serve as a surrogate model to study vascular permeability and reproductive disease, especially for these arenaviruses, at BSL-2." (PMID 39503743, 2024).
respiratory disease (1 paper, 2022). "Vitamins in respiratory disease reduce cellular load and expression of viral antigens, diminish the expression of interferon regulatory factor 3 (IRF3) and mitochondrial antiviral signaling (MAVS) genes, and increase the expression of NF-κB." (PMID 36293182, 2022).
IRF3 also shares sentences with these, for which no sentence is quoted: Cognitive impairment (4 papers); gastric tumor (4); acute kidney injury (3); chronic obstructive pulmonary disease (3); chronic pancreatitis (3); H1N1 virus infection (3); multiple sclerosis (3); viral diseases (3); acute monocytic leukemia (2); aortic aneurysm (2); atopic dermatitis (2); autoimmune thyroid disease (2); endometriosis (2); glaucoma (2); Hepatitis (2); hepatitis B (2); liver cirrhosis (2); malignant neoplasm of skin (2); prostate adenocarcinoma (2); systemic sclerosis (2); ulcerative colitis (2); acute liver failure (1); acute lymphoblastic leukemia (1); acute respiratory distress syndrome (1); age-related macular degeneration (1); alcoholic hepatitis (1); Allergy (1); amyotrophic lateral sclerosis (1); anemia (1); autoinflammatory syndrome (1).
A further 68 diseases each share a sentence with IRF3 in 1 paper.